RBAKDN (RBAK downstream neighbor)
Gene: Protein-coding gene on chromosome 7 (5,072,125 to 5,073,223, forward strand). Ensembl gene ENSG00000273313.
Subcellular location: Secreted
Diseases named in the same sentence as RBAKDN in open-access papers:
RBAKDN is named in the same sentence as 3 diseases in open-access papers, as found by Europe PMC text mining. Sharing a sentence is not in itself a finding about the gene and the disease. The quoted sentences say what the papers report.
cervical cancer (1 paper, 2023). A primary or metastatic malignant neoplasm involving the cervix. "The RBAKDN gene has been linked to the prognosis of patients with cervical cancer." (PMID 36992704, 2023).
cancer (1 paper, 2021). A tumor composed of atypical neoplastic, often pleomorphic cells that invade other tissues. "However, no studies have considered RBAKDN’s possible role in cancer." (PMID 33588862, 2021).
RBAKDN also shares sentences with these, for which no sentence is quoted: tumor (1 paper).